BCHE (butyrylcholinesterase)
Diseases named in the same sentence as BCHE in open-access papers (continued):
Sharing a sentence is not in itself a finding about the gene and the disease.
endometrial carcinoma (2 papers, 2022 to 2025). A malignant tumor arising from the epithelium that lines the cavity of the uterine body. "For example, BChE was identified as a critical and independent prognostic factor for endometrial carcinoma (EC) patients." (PMID 40678419, 2025). "The results also illustrated that BCHE levels were lower in endometrial carcinoma when compared to normal tissues." (PMID 35915658, 2022). "Based on our results, the BCHE expression compared to normal tissues was high in 7 kinds of cancer and low in 20 kinds of cancer including endometrial carcinoma." (PMID 35915658, 2022). "Nevertheless, no research has been conducted on BCHE's role in endometrial cancer." (PMID 35915658, 2022).
Hansen disease (2 papers, 2012 to 2025). "Hansen’s Disease (Leprosy) - Genetic studies showed that the frequency of the 70G allele and the D70G genotype of BChE (“atypical” phenotype) is higher in patients with Hansen disease (leprosy)." (PMID 40612057, 2025). "Here, we present results of an association study between leprosy and BCHE variants, including 70G, characterized by DNA genotyping." (PMID 22523498, 2012). "The present data suggest that the atypical BChE variant may predispose to leprosy per se." (PMID 22523498, 2012).
hepatocellular carcinoma (2 papers, 2025). A malignant tumor that arises from hepatocytes. "This study aimed to investigate the association between a new biomarker that incorporates albumin (Alb) and butyrylcholinesterase (BCHE) levels, as well as the prognosis of hepatocellular carcinoma (HCC) after hepatectomy." (PMID 39658717, 2025).
Hernia (2 papers, 2020 to 2021). "Using the Pig QTL database, two DE genes in both groups of hernias studied here were located in QTL regions already identified as being associated to SH hernia in pigs: the ACAN and BCHE genes were mapped, respectively, in the QTLs 55892 (SSC7) and 8794 (SSC13)." (PMID 33513662, 2021). "Among the DE genes in the two types of hernia, ACAN and BCHE (Butyrylcholinesterase) are highlight since they have already been located in QTL regions associated to scrotal/inguinal hernia." (PMID 33513662, 2021).
hypertriglyceridaemia (2 papers, 2005 to 2011). "BChE activity could also be used to select the drug for treatment of hypertriglyceridemia in T2DM." (PMID 21569551, 2011).
inflammatory bowel disease (2 papers, 2020 to 2025). A spectrum of small and large bowel inflammatory diseases of unknown etiology. "Weak TLR9 agonists, such as BL-7040, can upregulate miRNAs targeting BChE, offering a novel strategy to modulate inflammation in chronic inflammatory diseases like inflammatory bowel disease (IBD)." (PMID 40612057, 2025).
Inguinal hernia (2 papers, 2020 to 2021). Protrusion of the contents of the abdominal cavity through the inguinal canal. "Moreover, three other DE genes found in our study were located in QTL regions for scrotal/inguinal hernias: ACAN mapped in SSC7, Butyrylcholinesterase (BCHE) in SSC13 and KANK3 in SSC2." (PMID 32379844, 2020).
kidney carcinoma (2 papers, 2022 to 2025). Primary or metastatic malignant neoplasm involving the kidney. "Cytotoxic against the KM12 (colon), A498 (kidney carcinoma), and UO31 (renal) cancer cell lines, acetylcholinesterase (AChE), butyrylcholinesterase (BChE), and tyrosinase (TYR) inhibition activity." (PMID 40363722, 2025).
melanoma (2 papers, 2006 to 2025). A malignant, usually aggressive tumor composed of atypical, neoplastic melanocytes. "Of the genes correlated with shorter survival, some were already known to be over-expressed in different types of cancer, such as MCM3, BCHE, and some have previously been implicated in melanoma progression, like CSPG4 and Cx26 or, more generally, associated with tumor invasiveness, like ADAMTS5." (PMID 17129373, 2006). "This enzyme has also been studied in melanoma patients, where significant correlations were found between disease progression (including metastasis) and serum butyrylcholinesterase levels." (PMID 41155720, 2025).
pancreatitis (2 papers, 2024 to 2025). Inflammation of the pancreas. "Decreased BChE activity in blood plasma may be associated with a shorter survival time in pancreatitis patients." (PMID 40282999, 2025). "Finding secretagogue-specific inhibitory enzymes in the human pancreas that are analogous to BCHE in the canine, and blocking its associated receptors, may lead to a cure for human pancreatitis." (PMID 38996137, 2024). "If BCHE activity is completely inhibited then there is nothing to prevent all of the acinar cells ACh receptors from being occupied, and this will always result in hyperstimulation pancreatitis." (PMID 38996137, 2024). "Therefore, BChE could assist in determining the severity of pancreatitis." (PMID 40282999, 2025). "When BCHE activity is inhibited or destroyed, such as by administration of Diazinon in the canine, that regulatory mechanism becomes nonfunctional, and the canine always develops pancreatitis." (PMID 38996137, 2024).
pneumonia (2 papers, 2022 to 2024). An acute, acute and chronic, or chronic inflammation focally or diffusely affecting the lung parenchyma, caused by an infection in one or both of the lungs (by bacteria, viruses, fungi, or mycoplasma.). "All of our patients who died were in the severe pneumonia group, and BChE levels were found to be lower in these patients." (PMID 35957846, 2022). "There are not enough studies investigating the relationship between serum BChE level, mortality rate, and pneumonia severity in COVID-19 patients." (PMID 35957846, 2022). "The BChE level was median 13 (IQR: 11.2–21.5)ng/ml in patients with severe COVID-19 pneumonia and median 20 (IQR: 10–35.7)ng/ml in patients with mild to moderate pneumonia (p: 0.001)." (PMID 35957846, 2022). "Therefore, we can say that lower BChE levels in the severe pneumonia group are not related to age." (PMID 35957846, 2022).
respiratory failure (2 papers, 2021 to 2022). The significant impairment of gas exchange within the lungs resulting in hypoxia, hypercarbia, or both, to the extent that organ tissue perfusion is severely compromised. "We enrolled adults with respiratory failure and/or shock and measured plasma acetylcholinesterase (AChE) and butyrylcholinesterase (BChE) activity on days 1, 3, 5, and 7 after enrollment." (PMID 36474266, 2022).
Senile plaques (2 papers, 2007 to 2023). Senile plaques are extracellular deposits of amyloid in the gray matter of the brain. "The evidence is as follows; both human acetylcholinesterase (hAChE) and butyrylcholinesterase (hBuChE) are associated with senile plaques and both the pattern of hAChE oligomerisation and its enzymatic activity are altered in brain areas affected by AD." (PMID 17653279, 2007).
squamous cell carcinoma (2 papers, 2017 to 2019). A carcinoma arising from squamous epithelial cells. "Martinez-Moreno reported that BCHE activity decreased by 40–50% in adenocarcinoma, squamous cell carcinoma, and large cell carcinoma extracts." (PMID 28837649, 2017). "However, apart from low serum BChE levels, the only factors independently associated with shorter PFS and CSS in multivariate analyses were an advanced FIGO tumor stage, a larger tumor size, and a non-squamous cell carcinoma histology." (PMID 30737542, 2019).
Wilson disease (2 papers, 2022 to 2025). A very rare inherited multisystemic disease presenting non-specific neurological, hepatic, psychiatric or osseo-muscular manifestations due to excessive copper deposition in the body. "Therefore, the use of BCHE as a biomarker for Wilson’s disease (WD) has been proposed." (PMID 36291607, 2022).
acquired immunodeficiency syndrome (1 paper, 2018). "Butyrylcholinesterase (BChE) is synthesized mainly in the liver and an important marker in many infectious/inflammatory diseases, but its role in acquired immunodeficiency syndrome (AIDS) patients is not clear." (PMID 29736152, 2018).
acute lymphoblastic leukemia (1 paper, 2019). Leukemia with an acute onset, characterized by the presence of lymphoblasts in the bone marrow and the peripheral blood. "Considering the primary disease, only an association between acute lymphoblastic leukemia and BChE drop > 70% (p < 0.001) was detected." (PMID 31185690, 2019).
ameloblastoma (1 paper, 2022). The most common odontogenic tumor, arising from the epithelial component of the embryonic tooth and usually affecting the molar-ramus region of the mandible or maxilla. "With these bioinformatic analyses it is possible that pathogenic ameloblastoma development involve these genes in intracellular regulation (AKT1, ACTC1, ADAM10, and APOA2) or for tumor microenvironment regulation (CRP, BCHE, APP, AGT)." (PMID 36553196, 2022).
amnesia (1 paper, 2023). Pathologic partial or complete loss of the ability to recall past experiences ( AMNESIA, RETROGRADE) or to form new memories ( AMNESIA, ANTEROGRADE). "In the present study, compounds 30 and 33, developed earlier in our laboratory as selective butyrylcholinesterase inhibitors, were tested against scopolamine‐induced amnesia to evaluate their pharmacodynamic effect." (PMID 37786521, 2023).
Anal fistula (1 paper, 2024). An abnormal connection between the epithelialised surface of the anal canal and the perianal skin. "Butyrylcholinesterase, serving as a new predictive biomarker of postoperative complications following colorectal surgery, can be considered to detect the recurrence of anal fistulas." (PMID 39744085, 2024).
aneurysm (1 paper, 2023). Bulging or ballooning in an area of an artery secondary to arterial wall weakening. "Serum BDNF, TNF-α, caspase-3, AChE, and BChE levels were measured in 20 patients with spontaneous SAH due to aneurysms." (PMID 37873057, 2023).
Ascites (1 paper, 2015). Accumulation of fluid in the peritoneal cavity (between the layers of the peritoneum that lines the abdomen). "Measuring changes in the activity of the BChE related to the loss of body fluids (ascites) and regarding blood transfusion would be of further interest." (PMID 25762852, 2015).
atherosclerosis (1 paper, 2025). A disease characterized by the build-up of fatty material and calcium deposition in the arterial wall resulting in partial or complete occlusion of the arterial lumen. "In hypercholesterolemic patients, increased BChE levels are linked to decreased high-density lipoprotein (HDL) levels, an unfavorable association given HDL protective role against atherosclerosis." (PMID 40612057, 2025). "Similarly, in nonalcoholic fatty liver disease (NAFLD), the ratio of BChE to HDL correlates with disease severity and risk of atherosclerosis." (PMID 40612057, 2025).
autoimmune disease (1 paper, 2024). A disorder resulting from loss of function or tissue destruction of an organ or multiple organs, arising from humoral or cellular immune responses of the individual to their own tissue constituents. "Although the exclusion criteria (e.g., autoimmune diseases, severe psychiatric disorders) and anesthetic management were designed to minimize the risk of exposure to such medications, it cannot be ruled out that some drugs may have still influenced BChE activity." (PMID 39713214, 2024).
Bladder (1 paper, 2025). "miR-199a-5p: A Regulator of BChE in Bladder Pain Pathophysiology - Bioinformatic predictions suggest that miR-199a-5p may bind to the 3′-UTR of BChE mRNA, resulting in the downregulation of BChE activity." (PMID 40612057, 2025).
bone metastasis (1 paper, 2025). Transfer of a neoplasm from its primary site to bones. "Additionally, the study showed reduced BChE activity in all patient groups (localized and bone metastasis) relative to controls, with the greatest reduction observed in patients with bone metastasis." (PMID 40678419, 2025).
Bradycardia (1 paper, 2024). A slower than normal heart rate (in adults, slower than 60 beats per minute). "High doses of imidacloprid can inhibit butyrylcholinesterase, and when a patient has bradycardia and sweating, the doctor may mistake organophosphate poisoning for mixed organophosphates." (PMID 39114363, 2024).
brain malformations (1 paper, 2016). "Whether BCHE is a candidate gene for brain malformations remains to be elucidated." (PMID 27087860, 2016).
cocaine abuse (1 paper, 2018). Disorders related or resulting from use of cocaine. "This fact became clear to us as we followed long-term, group-housed, sibling male mice to determine the safety of interventions for sustaining elevated plasma levels of butyrylcholinesterase (BChE) to treat cocaine abuse." (PMID 28712092, 2018).
colon adenocarcinoma (1 paper, 2019). "BCHE p.T343fs has been reported in colon adenocarcinomas and esophageal carcinomas." (PMID 31595719, 2019).
colorectal adenocarcinoma (1 paper, 2025). The most common type of colorectal carcinoma. "In vitro assays were conducted to evaluate α-amylase, α-glucosidase, and BChE inhibition, RBC membrane stabilization, antibacterial activity against Helicobacter pylori and cytotoxicity using normal lung fibroblasts (WI-38) and human colorectal adenocarcinoma cell line (Caco-2)." (PMID 40872613, 2025).
complication (1 paper, 2019). Any disease or disorder that occurs during the course of, or because of, another disease, treatment, or procedure. "We looked at the association between the decrease in the absolute serum BChE activity values and the onset of transplant-related liver complications." (PMID 31185690, 2019). "Our results show that the reduction of BChE values below 2000 U/L the day before the transplantation is an indicator strongly associated with the transplant-related liver complications (p < 0.0001)." (PMID 31185690, 2019).
endometrial tumors (1 paper, 2022). "In contrast to normal tissues, endometrial tumors showed a low expression of BCHE and progressively higher expression as the disease progressed." (PMID 35915658, 2022).
esophageal squamous cell carcinoma (1 paper, 2023). Esophageal squamous cell carcinoma (ESCC) is a type of esophageal carcinoma (EC) that can affect any part of the esophagus, but is usually located in the upper or middle third. "Since previous studies described an association with various epithelial malignancies, observing the role of BChE in patients with esophageal squamous cell cancer and comparing the results to those with AEG patients might be of interest in further analysis." (PMID 37280384, 2023).
foot and mouth disease (1 paper, 2025). A viral infectious disease that results in infection in cattle and swine, has material basis in foot-and-mouth disease virus, which is transmitted by contaminated fomites, or transmitted by ingestion of food contaminated with infected meat or animal products. "Foot and Mouth Disease (FMD) - Increased BChE levels has been observed in cases of Foot and Mouth Disease (FMD) induced by enterovirus 71 infection in children." (PMID 40612057, 2025).
fungal infection (1 paper, 2018). "BChE is also an important clinical marker in inflammation, severe bacterial infection, and fungal infection." (PMID 29736152, 2018). "Low levels of BChE have also been noted in deep fungal infections, possibly due to enrichment of blood flow through the liver or invasion of fungi (e.g., Candida albicans, Candida tropicalis) into the liver from the gut by penetration through degenerated barriers of gastrointestinal mucosa." (PMID 29736152, 2018).
gallstones (1 paper, 2024). Solid crystalline precipitates in the biliary tract, usually formed in the gallbladder, resulting in the condition of cholelithiasis. "In addition, BChE activity may be associated with systemic inflammation and oxidative stress, which also play a role in gallstone development." (PMID 39399104, 2024).
glioma (1 paper, 2025). A benign or malignant brain and spinal cord tumor that arises from glial cells (astrocytes, oligodendrocytes, ependymal cells). "Interestingly, previous reports have described hybrid BChE-AChE molecular forms in human glioma." (PMID 41226363, 2025).
head and neck carcinoma (1 paper, 2015). A carcinoma that arises from the head and neck region. "Since smoking is strongly associated with head and neck cancer, correlation between tobacco exposure and level of expression of AChE and BChE mRNAs was assessed." (PMID 25956553, 2015). "As for BChE, the decreased enzyme activity in head and neck carcinomas contrasted with the increased mRNA levels in them." (PMID 25956553, 2015). "Contrary to AChE, BChE was found to be up-regulated in head and neck carcinoma as judged by the negligible level of BChE mRNA in ANCT and its strong increase in HNSCC." (PMID 25956553, 2015). "Moreover, the drop of AChE and BChE activities in head and neck cancers and the differences between ANCT and HNSCC pieces in AChE, BChE, nAChR and mAChR mRNA levels lent strong support to the notion that a non-neuronal cholinergic system may be involved in head and neck malignancy." (PMID 25956553, 2015).
HIV-1 infection (1 paper, 2017). The type species of lentivirus and the etiologic agent of acquired immunodeficiency syndrome (AIDS). "These correlative analyses suggest that the AChE activity of SE or other enzymes such as butyrylcholinesterase (BChE) that is capable of hydrolyzing acetylcholine may play a role in the SE-virus inhibitory interaction in the pre-incubation model of HIV-1 infection." (PMID 28338013, 2017).
Hyperhidrosis (1 paper, 2020). Abnormal excessive perspiration (sweating) despite the lack of appropriate stimuli like hot and humid weather. "It is associated with BCHE (butyrylcholinesterase), which is vital to ACh hydrolysis, and whose corresponding gene has been suggested as “interesting” with regard to hyperhidrosis, although no specific interactions are documented." (PMID 33378362, 2020).
immune complex disease (1 paper, 2023). "Genes involved in the complement cascade including glycosylphosphatidylinositol-specific phospholipase D1 (GPLD1), carnosine dipeptidase 1 (CNDP1) (in KEGG only), superoxide dismutase 3 (SOD3), and butyrylcholinesterase (BCHE) were also prominent in this immune complex disease." (PMID 37238213, 2023).
iron overload (1 paper, 2019). "In addition, severe iron overload was significantly related to BChE loss (p < 0.05), and abnormal baseline ferritin levels showed high predictive performance for the onset of transplant-related liver damage (AUC = 0.691; 95% CI = 0.62−0.76; p < 0.001)." (PMID 31185690, 2019). "In an analogous way, TBI-based conditioning and preexisting iron overload are a well-known risk factor for SOS, so it is not surprising that BChE reduction is more marked in these groups." (PMID 31185690, 2019).
ischemia (1 paper, 2019). A hypoperfusion of the BLOOD through an organ or tissue caused by a PATHOLOGIC CONSTRICTION or obstruction of its BLOOD VESSELS, or an absence of BLOOD CIRCULATION. "Specifically, it predicted roughly 22% less BChE activity in healthy controls carrying the CT genotype than in those carrying the CC genotype, while BChE activity was around 3% lower in patients with ischemia carrying the CT genotype than in those carrying the CC genotype." (PMID 31653081, 2019).
lactic acidosis (1 paper, 2023). Metabolic acidosis characterized by the accumulation of lactate in the body. "Amend N and coworkers administered 10 units of FFP within the first 4 days to an intoxicated patient who presented with hypotension, reduced kidney function, lactic acidosis and almost complete inhibition of serum BChE and had to be mechanically ventilated as a preventive measure." (PMID 37047631, 2023).
leukemia (1 paper, 2024). A malignant (clonal) hematologic disorder, involving hematopoietic stem cells and characterized by the presence of primitive or atypical myeloid or lymphoid cells in the bone marrow and the blood. "As a precursor of the auxin, tryptophol not only possesses hypnotic effect and reduces the production of Prostaglandin E2 (PGE2), TNFα, and IFNγ, but also inhibits the activity of butyrylcholinesterase and the proliferation of leukemia U937 cells." (PMID 38396889, 2024).